TNF (tumor necrosis factor)
Diseases named in the same sentence as TNF in open-access papers (continued):
Sharing a sentence is not in itself a finding about the gene and the disease.
pneumonia (continued). "For example, TNF-α induced by recruited monocytes is necessary for IL-17 production, macrophage phagocytosis, and bacterial clearance, and therefore, for facilitating recovery from pneumonia." (PMID 35370996, 2022). "Furthermore, a link between the respiratory microbiome and the TNFα levels in both pneumonia and ARDS patients has been reported." (PMID 36232913, 2022). "Finally, when comparing cytokine levels among the patients with HMPV pneumonia, IL-6 and TNF-α levels were found to be significantly higher in the severe group than the mild group (p = 0.027 and 0.049)." (PMID 36496397, 2022). "Finally, we proved that pretreatment with ATP combined with IFN-γ was safe and effective in a mouse model of acute pneumonia as evidenced by the significant reduction in alveolar inflammatory cell infiltration and reduced IL-1β and TNF-α levels." (PMID 36260750, 2022). "Furthermore, in an LPS-induced acute lung damage model, blocking TRPV4 function prevented pneumonia and decreased the generation of proinflammatory markers, including IL-6, TNF-α, and ROS." (PMID 36552524, 2022). "Intriguingly, in our recent report, the YHPGKL could play antiapoptosis during pneumonia, and this study also found that the effective hub components enable interaction with the TNF pathway." (PMID 36389108, 2022). "Moreover, glutamine synthesized by K. pneumonia leads to the elevated secretion of TNF-α in the lung normal fibroblast cells for a higher incidence of pneumonia." (PMID 36077725, 2022). "NF-κB and TNFα have long been known to be important for host defense and indeed have been shown to play a role in clearing extracellular bacteria in P. aeruginosa induced pneumonia." (PMID 33901267, 2021). "TNF is intimately involved in inflammatory pulmonary disease, including severe pneumonia and ARDS." (PMID 35264975, 2021). "It is up-regulated in patients’ plasma and may be involved in the progression of pneumonia by increasing the concentration of TNF-α and the activation of neutrophils." (PMID 34917619, 2021). "In in vivo models using mice with pneumonia induced by C. albicans, there was a reduction in the pro-inflammatory mediators IL-1β and TNF-α, as well as a decrease in the recruitment of leukocytes and neutrophils, when inhalable nanoemulsions containing EO of M. alternifolia were administered." (PMID 34683994, 2021). "In addition, alveolar monocytes from pneumonia-related ARDS had a significantly lower LPS-induced TNF expression than circulating monocytes issued from the same patients when expressed in percent of positive cells (p = 0.011)." (PMID 34944055, 2021). "Also, hepatic APPs exert liver protection by countering TNF-dependent toxicity in the liver and attenuate systemic inflammation and mortality in sepsis and pneumonia-induced ARDS." (PMID 33336286, 2020). "The Xue Bi Jing Injection relieved or reduced severe pneumonia by triggering the inflammation pathway through downregulation of TNF-α, IL-6, and IL-8 on the 3rd, 7th, and 14th day after treatment, although it did not significantly influence the release of leptin." (PMID 33746739, 2020). "Furthermore, H1N1 infection caused significant elevation of mRNA levels by up to 3-6-fold for IL-1β, IL-6, and TNF-α, reinforcing the successful establishment of virus-induced pneumonia." (PMID 32901688, 2020). "A murine model of pneumonia was used to assess whether the differences seen in cell culture in TNF responses to S. pneumoniae reflected differences during disease." (PMID 31551336, 2019). "Our present results illustrated that co-administration of MSC and LZD significantly decreased the plasma concentrations of systemic cytokines such as CRP, IL-8, IL-6, and TNF-α in MRSA-induced pneumonia compared with LZD treatment alone, which were in line with previous report." (PMID 31484796, 2019). "The TIGR4 strain induces stronger early TNF responses in a mouse model of pneumonia." (PMID 31551336, 2019).
pneumonia (continued). "In contrast to the enhanced levels of the pro-inflammatory cytokines IL-8 and TNF-α, significantly lower levels of secreted IL-1β were observed in cultures derived from patients with A-T as compared to healthy controls post-infection with S. pneumonia." (PMID 30796268, 2019). "However, more investigations are necessary to fully elucidate the role of TNF-α in the development of pneumonia because its real implication is not completely understood." (PMID 30884861, 2019). "Although TNF decreases amiloride-sensitive current as well as the steady-state mRNA and protein levels of ENaC in adult alveolar epithelial cells, the cytokine has also been shown to increase alveolar fluid clearance in a rat pneumonia model." (PMID 29439494, 2018). "In conditions of severe pneumonia in patients serum levels of TNF and IL-6 reach ng quantities." (PMID 28642550, 2017). "However, and in contrast, we observed a rising systemic inflammatory response (i.e., plasma levels of IL-8 and TNF-α), as early as the 8th hour only in animals with pneumonia subjected to MV." (PMID 27391952, 2016). "This may be attributed to large amounts of inflammatory cytokines, including tumor necrosis factor (TNF)-α, interleukin (IL)-1 and IL-6, which are present during critical pneumonia." (PMID 26928863, 2016). "IL-1β is associated with severity of infection, IL-6 reflects the severity of stress, and TNF-α may be a marker of pneumonia severity." (PMID 25815231, 2015). "Conversely, the level lung IL-10 were increased starting at 2 hours after initiation of AZM alone or in AMP plus AZM treated mice and sustained up to 6 hr post antibiotic treatment when compared to S. pneumonia infected untreated group (A: IL-6; B: IL-10; C: TNF-α and D: IFN-γ)." (PMID 24565171, 2014). "Collectively, these results suggested that TNF-α might have an important role in the pathophysiology of pneumonia." (PMID 23577187, 2013). "For TNF-α −308A/G polymorphism and pneumonia risk, no significant between-study heterogeneity was observed in the dominant genetic model (Pheterogeneity = 0.13 and I2 = 33%)." (PMID 23577187, 2013). "In addition, systemic administration of TNF-α in rat worsened pneumonia by reducing alveolar neutrophil recruitment and bacterial clearance." (PMID 23577187, 2013). "Systemically, pneumonia caused modest inflammation, with increased plasma levels of IL-6, but not of TNF–α, IL-1β and CINC3 when compared to non-infected controls (p<0.05)." (PMID 23717435, 2013). "Here, we demonstrated that both salmeterol and salbutamol dose-dependently inhibit TNFα release by mouse alveolar macrophages stimulated with NTHi in vitro and that inhalation of either β2 agonist was associated with lower TNFα concentrations in lung tissue and BALF during NTHi pneumonia in vivo." (PMID 16595015, 2006). "Lethally irradiated TNF-KO mice reconstituted with bone marrow cells from mem-TNF mice controlled Mtb infection as demonstrated by survival over three months, while TNF-KO mice succumbed to acute necrotic pneumonia within 40 days." (PMID 16285886, 2005). "However, during the chronic phase of infection mem-TNF mice succumbed to disseminated infection with necrotic pneumonia at about 150 days." (PMID 16285886, 2005). "Using PCR-DNA sequence verdicts, the IL-1α (356-bp), IL-1β (423-bp), IL-6 (384-bp), TNFα (490-bp), IL-10 (306-bp), IFN-γ (321-bp), PRDX6 (434-bp), ATG7 (416-bp), NDUFS6 (405-bp), and NOX4 (396-bp) genes were found to have different SNPs in the amplified DNA bases linked to pneumonia." (PMID 40711280, 2025). "In this study, the results showed that IL-1β, IL-6 and TNF-a in control group were lower than those of the model control group, and there were extremely significant statistical differences (p < 0.001), indicating that LPS-induced zebrafish pneumonia models elevated inflammatory factors." (PMID 40271073, 2025). "Moreover, HSP70 and TNF-a have good predictive values for ARDS in children with pneumonia." (PMID 41382116, 2025).
pneumonia (continued). "Therefore, future studies should consider increasing sample size, standardizing efficacy evaluation criteria, and further exploring the stratified role of IL-6 and TNF-α levels in severe pneumonia patients to enhance the reliability and applicability of the results." (PMID 40342990, 2025). "The cytokines IL-1β, IL-6, and TNF-α, which are key indicators of inflammation, were found to be elevated in the model control group compared to the control group, with extremely significant statistical differences, confirming the inflammatory nature of the LPS-induced pneumonia model." (PMID 40271073, 2025). "Pneumonia may use CRP as a clinical measure instead of TNF-alpha or IL-6." (PMID 39727640, 2024). "The large inflammatory response in SARS-CoV-2-induced pneumonia is due to the overactivation of the immune system, resulting in a "cytokine storm" characterized by the excessive release of inflammatory cytokines, such as interleukin-6 (IL-6) and tumor necrotic factor-alpha (TNF-α)." (PMID 38021879, 2023). "A retrospective study of people with IBD using the American Veteran Affairs dataset revealed anti-TNF therapies are associated with an increased risk of pneumonia and hospitalization; though this was not stratified by age, 36.5% of persons in this study were >64 years." (PMID 37674503, 2023). "Importantly, our results implied that the TNF signaling pathway might be a potential mechanism by which YHPGKL treats pneumonia, which will be confirmed." (PMID 36389108, 2022). "Notably, significantly higher plasma levels of IL-2, IL-7, IL-10, G-CSF, IP-10, MCP-1, MIP-1α, and TNFα were found in patients with severe pneumonia developing ARDS and required ICU admission and oxygen therapy compared to non-ICU patients showing pneumonia without ADRS." (PMID 34639132, 2021). "Pneumonia development was associated with the release of large amounts of IL-8 and TNF-α within the lung, whether rabbits underwent MV or not." (PMID 29149185, 2017). "The same anti-TNFα antibody that strongly impaired host defense during pneumonia caused by S. pneumoniae or K. pneumoniae did not influence the bacterial load during NTHi pneumonia." (PMID 16595015, 2006). "When comparing pneumonia-affected sheep to resistant ewes, the IL-1α, IL1B, IL6, and TNF-α genes were markedly upregulated." (PMID 40711280, 2025). "In an LPS-induced acute pneumonia mouse model, THC significantly inhibited neutrophil migration and reduced neutrophil elastase, TNF-alpha, and IL-6 levels." (PMID 40599866, 2025). "These lung-protective mechanisms can be activated by a direct ENaC activator, the TNF-derived TIP peptide, in models of pneumococcal and SARS-CoV2-induced pneumonia." (PMID 40260205, 2025). "The concentrations of cytokines often also followed this pattern, although female wild type mice with pneumonia did have increased concentrations of MCP-1, TNF-α and IL-12 (p40) compared to males of the same genotype." (PMID 40238852, 2025). "The genes IL-1α, IL1B, IL6, TNF-α, IL10, IFN-γ, and NOX4 had significantly greater gene expression levels in pneumonia-affected calves compared to the CON group." (PMID 40711280, 2025). "HSP-70 had 93.3% sensitivity and 91.1% specificity at cutoff point of 5.5 ng/ml and TNF-α had 93.3% sensitivity and 86.7% specificity at a cutoff point of 442 pg/ml to predict ARDS in children with pneumonia." (PMID 41382116, 2025). "Our investigation used a PCR-DNA-sequencing procedure to illustrate the difference in immunological (IL-1α, IL1B, IL6, TNF-α, IL10, and IFN-γ) and antioxidant (PRDX6, ATG7, NDUFS6, and NOX4) genes in calves with pneumonia and healthy calves." (PMID 40711280, 2025). "Similar results were found with a PspA-Ply fusion protein-based vaccine in mice: a significant production of TNF-α and IL-6 in the bronchoalveolar lavage fluid (BALF) was observed, correlating with protection against pneumonia." (PMID 38400196, 2024).
pneumonia (continued). "Transcriptomics identified the TNF, PI3K/AKT, HIF-1, and NF-κB signaling pathways as the primary targets of SHQXW in treating KP-induced pneumonia." (PMID 39474608, 2024). "This makes it a practical option for screening and monitoring pneumonia compared to complex or expensive biomarkers, such as CRP, IL-6, and TNF-a." (PMID 38404841, 2024). "The analyses demonstrated that the signals of TNF-α/NFκB and MAPK were high in the PBMC transcriptome in the presence of pneumonia." (PMID 39205185, 2024). "In vitro analyses revealed substantial reductions in the secretions of tumor necrosis factor-α and interleukin-6 from alveolar macrophages, highlighting the potential efficacy of DXMS-Pal-SLNs in alleviating pneumonia-related inflammation." (PMID 39065575, 2024). "In IBD, drug-induced pneumonias are mainly related to purine analogues (Azathioprine, 6-mercaptopurine), 5-ASA derivates (mesalazine, sulfasalazine), Methotrexate, and anti-tumor necrosis factor (TNF) alpha." (PMID 39112694, 2024). "In a M. pneumoniae pneumonia mouse model, TFCO significantly reduced the lung damage, suppressed IL-1β, IL-6, and TNF-α production, and curbed TLR2 activation triggered by M. pneumoniae." (PMID 37894556, 2023). "The study demonstrated that pneumonia symptoms were significantly attenuated in QKL-treated rats, including decreased TNF-α, NO levels and increased SOD level." (PMID 37362920, 2023). "Enzyme‐linked immunosorbent assay (ELISA) was used to detect the levels of tumor necrosis factor‐α (TNF‐α), interleukin (IL)‐1β, NLRP3, and LL‐37 in the sera of healthy subjects, children with KD, and children with pneumonia." (PMID 37773705, 2023). "Seven hub genes, IL4, IL6, CSF2, IFNG, IL1B, TNF and IL17A, were responsible for Experimental Lung Inflammation, Pneumonitis, Pneumonia and Lobar Pneumonia." (PMID 36989283, 2023). "Furthermore, using a mouse pneumonia model induced by LPS showed that compounds 4–6 and 12 as well as baicalein and ivermectin could inhibit the infiltration of inflammatory cells and the secretion of inflammatory cytokines IL-8, TNF-α, and NO." (PMID 37630304, 2023). "The ELISA results measuring the concentrations of TNF-α and IL-1β in the BALF revealed a significant increase in the production and release of these cytokines in LPS-induced pneumonia, leading to a heightened inflammatory response in the lung tissues." (PMID 37446875, 2023). "In our study, the serum levels of TNF‐α, IL‐1β, and NLRP3 were significantly elevated in children with KD and pneumonia compared with healthy subjects." (PMID 37773705, 2023). "The analysis results indicated IL-6 and TNF-α were effective biomarkers to differentiate between mild and severe symptoms in children diagnosed with HMPV pneumonia with an AUC of 0.678 (95% CI 0.526–0.829) and 0.658 (95% CI 0.506–0.809), respectively." (PMID 36496397, 2022). "Compared with the model group, isorhamnetin reduced the protein expressions of SYK, IL-6, MAPK14, MAPK8, TNF-α, AKT, p-Akt, PIK3CA, EGFR and IL-1β in lung tissues of pneumonia mice." (PMID 36506534, 2022). "A multiplex-biometric immunoassay showed that pneumonia cases had higher levels of serum cytokines (G-CSF, IL-2, IL-6, IL-10, IL-18, IP-10, MCP-3, and TNF-α) than bronchitis cases." (PMID 36119044, 2022). "These available results suggested glutamine produced by K. pneumonia prompted TNF-α expression of WI38 cells, thereby accelerating pneumonia." (PMID 36077725, 2022). "We detected significant production of TNF-α and IL-6 in the BALF, which correlated with protection against pneumonia in the group immunized with rPspA-PlD1." (PMID 36477013, 2022). "The IL-6 and TNF-α were used to differentiate between mild symptoms and severe symptoms in children diagnosed with HMPV pneumonia with an AUC of 0.678 (95% CI 0.526–0.829) and 0.658 (95% CI 0.506–0.809), respectively." (PMID 36496397, 2022).
pneumonia (continued). "Inflammatory cytokines induced by pneumonia‐related bacteria, such as Haemophilus influenzae and Streptococcus pneumoniae, are important in COPD exacerbation, and TNF‐α and IL‐6 levels are increased in sputum during COPD exacerbations." (PMID 35034433, 2022). "It has a therapeutic impact on pneumonia model rats by reducing B lymphocytes, CD8+ ratio, and elevated levels of IL-1α, IL-1β, IL-2, IL-10, TNF-α, IFN-α, IFN-γ, IgM, IgG, CD4+/CD8+, and NK cells." (PMID 36388945, 2022). "Increased inflammatory cytokines, such as interleukin-6 (IL-6) and tumor necrosis factor alpha (TNF-α), are indeed observed in patients with severe pneumonia." (PMID 36135185, 2022). "In contrast, during the recovery period of the pneumonia group, such as for cases P1, P2, and U1, there were decreases in certain cytokines, such as IL-2, IL-6, MCP-3, and TNF-α." (PMID 36119044, 2022). "The results of KEGG enrichment uncovered the numerous signaling pathways involved in the development and progression of pneumonia, including PI3K-Akt, HIF-1, IL-17, TNF, TLR, JAK–STAT, NOD-like receptor, or MAPK." (PMID 35891565, 2022). "As such, TNF at early time points following G– pneumonia can upregulate net AFC, partly by a TNF-dependent mechanism." (PMID 35264975, 2021). "Pathological examinations and cellular profiles of BALF showed that H-AASD exacerbated pneumonia incidence in KP infected mice and increased expression of cytokines (IL-1β, IL-6, IL-12, IFN-γ, TNF-α) and chemokines (KC, MCP-1, MIP-1α) related to KP in BALF." (PMID 34333291, 2021). "When compared to mild disease, patients that developed severe pneumonia had a significant increase in IL1-RA, IL-6, IP-10, MCP-1, MCP-3, M-CSF, and TNF-α." (PMID 34131192, 2021). "Second, the lectin-like domain of TNF which is spatially distinct from the receptor binding sites exerts largely protective activities in ARDS and severe pneumonia upon binding to ENaC-α." (PMID 35264975, 2021). "For example, potentially useful biomarkers for severe or refractory pneumonia include AST, ALT, LDH, CRP, ferritin, and various cytokines (IL-18, IL-6, or TNF-α)." (PMID 33810090, 2021). "Shufeng Jiedu prescription also played a significant role in regulating immune function by significantly reducing the levels of IL-1α, IL-1β, IL-2, IL-4, IL-10, TNF-α, interferon (IFN)-α, and IFN-γ in a rat model of streptococcus pneumoniae-induced pneumonia." (PMID 34861881, 2021). "Monocytes from pneumonia-related ARDS patients have a deactivated status and an impaired TNF production capacity but display potent phagocytic activity." (PMID 34944055, 2021). "TNF-α and TGF-β are important indicators of LPS-induced pneumonia, and their increase can reflect the state of pneumonia, especially as TGF-β is considered to be important for fibrosis." (PMID 34367295, 2021). "Previous clinical studies reported that the circulating levels of pro-inflammatory cytokines, including tumor necrosis factor-α (TNF-α), IL-6, and IL-8, are generally elevated in patients with pneumonia." (PMID 34768890, 2021). "Among them, 23 target proteins such as PTGS2, TNF and FOS were enriched in the IL-17 signalling pathway, indicating that the IL-17 signalling pathway plays an important role in the treatment of pneumonia by RYNM." (PMID 33678123, 2021). "After treatment with Bm (75, 150, and 300 μg/kg), TNF-α, IL-6, IL-1β, and PEG2 levels in Kp-induced pneumonia mice exhibited a downward trend in a dose-dependent manner." (PMID 34017253, 2021). "Further, increases in IL-6, IL-8, IL-10, IL-15, TNF-α, and IFN-γ have been reported in severe pneumonia compared with mild pneumonia." (PMID 34692846, 2021). "Then, the expressions of 25-OH-VD, VDR, TGFβ, IL-2, IFN-γ, TNFα, IL-1β, Ca2+, PCT, CRP, and IL-6 in mild pneumonia, severe pneumonia, and healthy controls were determined using qRT-PCR, western blot, ELISA, and calcium colorimetry assay." (PMID 34643152, 2021).